CXCR4 (C-X-C motif chemokine receptor 4)
Diseases named in the same sentence as CXCR4 in open-access papers (continued):
Sharing a sentence is not in itself a finding about the gene and the disease.
Burkitt lymphoma (7 papers, 2011 to 2022). A rare form of malignant mature B-cell non-Hodgkin lymphoma. "For consistency between previous studies, we used the Daudi Burkitt lymphoma xenograft model, which has shown to have robust CXCR4 and comparable CXCR4 expression as compared to other hematological malignancies." (PMID 35890397, 2022). "We determined affinity and saturation binding of Ulocuplumab (BMS-936564) to CXCR4 using a radiolabeled antibody 125I-BMS-936564 in Ramos cell line (Burkitt's lymphoma)." (PMID 26646452, 2016). "In Burkitt lymphoma, the CXCR4 antagonist plerixafor has already been shown to enhance the therapeutic effect of rituximab, the immunotherapeutic agent of R-CHOP; but this is yet to be confirmed for DLBCL." (PMID 27307990, 2016). "The human Burkitt's lymphoma cell line NC-37, which expresses CXCR4, CXCR5, CXCR7 and CCR7, was selected as a model system." (PMID 21672222, 2011). "Furthermore, we observed that AMD070 and its niacin derivative WK1 had pro-apoptotic effects in the CXCR4+ Burkitt lymphoma and one CXCR4+ GCB-DLBCL cell line as demonstrated by functional assays and gene expression analysis." (PMID 31554271, 2019). "In Burkitt lymphoma and chronic lymphocytic leukemia (CLL), the effect of rituximab was enhanced when antagonizing CXCR4 and, recently, we reported a synergistic effect when administering the CXCR4 antagonist plerixafor concomitantly with rituximab to DLBCL cells in vitro." (PMID 30774774, 2019).
chronic kidney disease (7 papers, 2014 to 2024). Impairment of the renal function secondary to chronic kidney damage persisting for three or more months. "Analysis of another public chronic kidney disease (CKD) data set also revealed that CXCL12/CXCR4/C3 was highly correlated with the severity of CKD." (PMID 38716725, 2024). "The study aimed at flow cytometric analysis of T cell subsets with selected surface chemokine receptors (CCR4, CCR5, CCR7, CXCR3, and CXCR4) or receptor combination in peripheral blood of children with chronic kidney disease (CKD) on hemodialysis (HD)." (PMID 25866451, 2015).
cutaneous melanoma (7 papers, 2007 to 2023). A primary melanoma arising from atypical melanocytes in the skin. "Cutaneous melanoma immunohistocemical studies have also shown that CXCR4 is a predictor of poor prognosis." (PMID 18001467, 2007). "Further studies have analyzed the expression of CXCR4 in metastasis of human cutaneous melanomas, and have conferred active CXCR4 expression and displayed the possibility of interfering with this axis in order to inhibit metastasis using a novel inhibitor AMD3100." (PMID 18001467, 2007).
dementia (7 papers, 2013 to 2024). Loss of intellectual abilities interfering with an individual's social and occupational functions. "Moreover, they cover genes previously implicated in PD relevant phenotypes such as dementia (CXCR4) and neurodegeneration (MAPK1) (see Discussion section for details on prior functional implications of these genes in PD and molecular sex differences)." (PMID 36681675, 2023). "For example, Cxcr4 acts also as a main co-receptor for cellular entry of T-tropic strains of HIV-1 at late stages of infection and in individuals with acquired immune deficiency syndrome-associated dementia complex (ADC), who develop a spectrum of motor impairments and dementia." (PMID 28100513, 2017).
diabetic neuropathy (7 papers, 2014 to 2024). A chronic, pathological complication associated with diabetes mellitus, where nerve damages are incurred due to diabetic microvascular injury involving small blood vessels that supply these nerves, resulting in peripheral and/or autonomic nerve dysfunction. "An emphasis was placed on the role of CXCR4 in diabetic neuropathy, a common cause of painful diabetic neuropathy (PDN)." (PMID 39070795, 2024). "It was earlier reported that CXCR4 chemokine receptor signaling mediates pain in diabetic neuropathy." (PMID 36297381, 2022). "Collectively, these findings suggest the interaction between TLR4/MyD88/NF-κB signaling pathways and CXCR4 plays an important role in the diabetic neuropathy." (PMID 30647535, 2018). "Therefore, the study suggests a possible involvement of the MALAT1/CXCR4 axis in the pathogenesis of diabetic neuropathy." (PMID 36297381, 2022). "In addition, another HMGB1‐specific inhibitor, glycyrrhizin reverses the upregulation of HMGB1 and its receptors (TLR4 and CXCR4) in mice with diabetic neuropathy, improving mechanical and thermal pain threshold in these animals." (PMID 35706377, 2022). "Importantly, CXCR4 expression is increased in a peripheral nerve microarray analysis from diabetic patients with progressive diabetic neuropathy, implicating CXCR4/SDF-1 signaling in the pathogenesis of diabetic neuropathy in humans." (PMID 24961298, 2014). "Our study shows that the release of HMGB1 might be involved in the activation of JNK pathways and blocking the release of HMGB1 by GLC may impede pain through alterations in CXCR4 mediated pain pathways, which could be an advantageous therapeutic approach for diabetic neuropathy." (PMID 32019145, 2020).
endothelial dysfunction (7 papers, 2010 to 2025). In vascular diseases, endothelial dysfunction is a systemic pathological state of the endothelium (the inner lining of blood vessels) and can be broadly defined as an imbalance between vasodilating and vasoconstricting substances produced by (or acting on) the endothelium. "Finally, we assessed if vessels transfected with LAV‐BPIFB4 are protected from high glucose‐induced endothelial dysfunction through a CXCR4‐mediated mechanism." (PMID 32384208, 2020). "The reduced number of cells expressing CXCR4 and CXCR7 likely results in the reduced ability to migrate into circulation and to ischemic tissue within diabetes, which may further exacerbate endothelial dysfunction and microvascular abnormalities and increase the risk of mortality." (PMID 34267242, 2021).
lupus nephritis (7 papers, 2012 to 2026). Glomerulonephritis in the context of systemic lupus erythematosus. "CXCR4 also appears crucial for pathogenic B cell accumulation in the kidneys in lupus nephritis." (PMID 34889940, 2022). "Combined DPP-4 and CXCL12/CXCR4 axis inhibition synergistically enhanced podocyte protection and attenuated renal inflammation, fibrosis, and oxidative stress in lupus nephritis." (PMID 41601976, 2026). "To elucidate the role of CXCL12/CXCR4 axis in lupus nephritis, we assessed CXCL12 expression in renal tissues at different disease stages." (PMID 41601976, 2026). "AMD3100 or its derivatives have been shown to inhibit the migration of CXCR4+ cells into the synovial fluid of RA patients, reduce neovascularisation, and lessen the severity of lupus nephritis in an arthritic mouse model." (PMID 39779470, 2025). "While there is a relative consensus on CXCR4 anomaly in B cells of several mouse models of lupus nephritis, the situation is still unclear in humans." (PMID 23244336, 2012). "In addition, a higher frequency of CXCR4-positive B cells is found in the interstitial lesions of lupus nephritis." (PMID 38519141, 2024). "Transfer of murine TLR4+CXCR4+ plasma cells into RAG-2–deficient mice induces autoantibody production and immune complex glomerulonephritis, demonstrating the role of these cells in lupus nephritis pathogenesis." (PMID 38519141, 2024). "Thus, in concert with CXCL12, CXCR4 could be pivotal for leukocyte trafficking into damaged kidneys from mice with lupus nephritis." (PMID 23244336, 2012). "In mouse models with active lupus nephritis, such as MRL/lpr or BXSB mice, a strain in which TLR7 is overexpressed, an increase in the expression of CXCR4 on the surface of B cells is observed." (PMID 38519141, 2024). "Chemokines and chemokine receptors are used as therapeutic targets in lupus nephritis; therefore, we assessed the surface expression of the most important chemokine receptors (CCR6, CCR7, CXCR4 and CXCR5) on B lymphocytes from all four groups by flow cytometry." (PMID 25909640, 2015). "Interestingly, CXCR4 is also a target in lupus glomerulonephritis and the levels of interferon-γ in this disease are elevated without the use of a CXCR4 antagonist." (PMID 33676416, 2021).
lymphoplasmacytic lymphoma (7 papers, 2020 to 2026). A clonal neoplasm of small B-lymphocytes, lymphoplasmacytoid cells, and plasma cells involving the bone marrow, lymph nodes, and the spleen. "Further, the mutational status of CXCR4 in lymphoplasmacytic lymphoma (LPL) has been shown to influence disease burden and response to targeted therapies, further underscoring the prognostic role of genomic alterations." (PMID 40150070, 2025). "BM biopsy demonstrated lymphoplasmacytic lymphoma with λ-restricted plasma cells, and molecular studies were negative for MYD88 L265P and CXCR4 mutations." (PMID 42282257, 2026). "Therefore, the CXCR4-targeted PET/CT imaging with [68Ga]pentixafor may become an important tool for diagnosis and staging of lymphoplasmacytic lymphoma." (PMID 32757068, 2020).
MALT lymphoma (7 papers, 2015 to 2025). An indolent, extranodal type of non-Hodgkin lymphoma composed of small B-lymphocytes (centrocyte-like cells). "CXCR4, however, was substantially upregulated in more than 90% of samples obtained from extranodal MZL of mucosa-associated lymphoid tissue lymphoma." (PMID 37943339, 2024). "Notably, CXCR4 was frequently detected in nodal MALT lymphoma, and nodal DLBCL patients with a bone marrow infiltration, but was not expressed in the tumor cells of patients with gastric lymphoma." (PMID 30999581, 2019). "Furthermore, CXCR3, CXCR4, and CXCR5 have been implicated in the pathogenesis of MALT lymphoma." (PMID 39451532, 2024). "This, together with the provided benefit of CXCR4-targeted PET/CT as summarized above, led the experts to suggest that [68Ga]PentixaFor PET might serve as a valuable diagnostic tool for MZL including MALT lymphoma, and should be further developed in prospective clinical trials." (PMID 38190998, 2024). "In this study all MALT lymphomas were negative for all SSTR receptors and CXCR4." (PMID 34307181, 2021).
mesothelioma (7 papers, 2015 to 2021). A usually malignant and aggressive neoplasm of the mesothelium which is often associated with exposure to asbestos. "Robust upregulation of CXCR4 was reported in human mesothelioma cell lines and in mesothelioma tissues." (PMID 33956406, 2021). "In malignant mesothelioma, robust overexpression of CXCR4 was reported in human mesothelioma cell lines and the majority of mesothelioma tissues, respectively." (PMID 29228566, 2017). "Strikingly, IHC for CXCR4 was principally positive in 5 of 6 human mesothelioma cell lines as well as 31/41 mesothelioma tissues." (PMID 29228566, 2017). "CXCR4 was found in almost all mesotheliomas (97%) and CXCL12 in 78%; another receptor, CXCR7, was only weakly expressed." (PMID 26078352, 2015). "Furthermore, CXCR4 inhibitor in combination with an immune-activating fusion protein called VIC-008 suppresses mesothelioma growth by inhibiting PD-1 expression in CD8+ T cells and promotes transition of Tregs into T helper cells." (PMID 31584877, 2019). "In cell culture experiments, Li and co-workers could also demonstrate that CXCL12, the sole ligand of CXCR4, can induce proliferation in mesothelioma which can be antagonized by administration of CXCR4 inhibitors such as AMD3100." (PMID 29228566, 2017). "Thus, potentially differential CXCR4 expression by different histologic mesothelioma subtypes (e.g. sarcomatoid mesothelioma) might have been missed." (PMID 29228566, 2017). "In our study we could not determine any changes in the cell surface expression level of CXCR4 on PDA30364/OVA cells in response to irradiation with single doses from 1 to 10 Gy, which differs from results reported for mesothelioma cells." (PMID 31959787, 2020). "Nine additional surgical mesothelioma samples from patients not undergoing CXCR4-directed imaging were available for analysis." (PMID 29228566, 2017). "Thus, our findings are in line with a previous study reporting on a rather lower CXCR4 expression profile of solid cancers and metastases (not including mesothelioma) in vivo." (PMID 29228566, 2017).
pituitary adenomas (7 papers, 2012 to 2022). "An activated CXCL12/CXCR4 axis has also been associated with proliferation of pituitary adenomas." (PMID 22349813, 2012). "Accordingly, we discuss the potential targeting of CXCR4 as novel pharmacological approach for pituitary adenomas." (PMID 25484899, 2014). "Both CXCL12 and CXCR4 are constitutively overexpressed in pituitary adenomas and their signalling induces cell survival and proliferation, as well as hormonal hypersecretion." (PMID 25484899, 2014). "CXCR4 mRNA is expressed in almost all GH-secreting pituitary adenomas and in the great majority of NFPAs, whilst CXCL12 was identified in about 2/3 of these tumors." (PMID 25484899, 2014). "Overall, these observations imply that CXCL12/CXCR4 axis might play an important biological role in pituitary adenoma as potential growth and angiogenic factor for pituitary cells." (PMID 25484899, 2014). "Consequently, alterations of the endocrine regulatory pathways due to upregulation of hypothalamic/pituitary CXCL12/CXCR4 axis might lead to the development of pituitary adenomas." (PMID 25484899, 2014). "Consistent with our findings are extensive studies using single cells isolated from human pituitary adenomas to show increased expression of stem cell markers SOX2 and CXCR4." (PMID 36359740, 2022). "CXCL12 secretion from CXCR4 expressing cells supports the occurrence of autocrine/paracrine mechanism in GBM CSCs, in human meningioma and pituitary adenoma cells." (PMID 30564115, 2018). "Moreover, interactions between CSCs and tumor microenvironment through secreted CKs (e.g., CXCL12), possibly occurring also in pituitary adenomas, may act as chemoattractant to recruit fibroblasts, endothelial, mesenchymal, and inflammatory cells to the tumor, via CXCR4." (PMID 25484899, 2014). "Another study shows that CXCR4 mRNA is expressed in 92% of growth hormone secretory pituitary adenomas (GHoma) and 81% NFPAs, whereas SDF1 is found in 63% of GHomas and 78% of NFPAs; and CXCR4 and SDF1 are the strong homogenous markers in all tumor cells of GHomas and NFPAs." (PMID 31920968, 2019). "Finally, the evaluation of CXCR4 and CXCL12 expression in invasive and noninvasive pituitary adenoma specimens, by flow cytometry and immunohistochemical staining, demonstrated that the percentage of CXCR4- and CXCL12-positive cells was significantly higher in invasive pituitary adenomas." (PMID 25484899, 2014). "Interestingly, GH4C1 rat pituitary adenoma cell line expresses CXCR4 but not CXCL12, thus it was proposed as a suitable model to characterize the molecular pathways regulated by this receptor in pituitary adenomas, without the interference of the endogenously released CK." (PMID 25484899, 2014). "However, such generalized CXCR4 and CXCL12 overexpression in human pituitary adenomas, as compared to normal pituitary, strongly suggests that, in conditions of deregulation, this receptor system could be a relevant factor for pituitary adenoma development and/or progression." (PMID 25484899, 2014).
primary aldosteronism (7 papers, 2025 to 2026). An endocrine disorder characterized by excessive production of aldosterone by the adrenal glands. "Recent studies used CXCR4 as a probe for 68Ga-pentixafor positron emission tomography (PET)/CT imaging in patients with primary aldosteronism who were to undergo laparoscopic surgery." (PMID 40815389, 2026). "For the first time, we integrated this novel CXCR4-based imaging approach into the diagnosis and treatment paradigm for primary aldosteronism." (PMID 40815389, 2026). "Several previous studies have underscored the significance of targeted CXCR4 PET/CT in subtyping the diagnosis of primary aldosteronism (PA); however, their focus was solely on 68Ga-pentixafor." (PMID 40084145, 2025). "In patients with primary aldosteronism coexisting with Cushing’s syndrome or receiving exogenous glucocorticoid supplementation, CXCR4 imaging is more suitable than AVS for determining lateralization." (PMID 39375255, 2025). "Our study also demonstrated that APA patients had significantly higher LCR than MAPN/MAPM patients, indicating the potential value of CXCR4 PET/CT in pathological subtype diagnosis of primary aldosteronism." (PMID 40246740, 2025). "Thus, this study underscores the indispensable value of CXCR4-based imaging for advancing the management of primary aldosteronism." (PMID 40815389, 2026). "CXCR4 PET/CT imaging has emerged as a tool for diagnosis and subtyping of primary aldosteronism (PA)." (PMID 40246740, 2025).